IRS1 (insulin receptor substrate 1)
Diseases named in the same sentence as IRS1 in open-access papers (continued):
Sharing a sentence is not in itself a finding about the gene and the disease.
Insulin resistance (continued). "Increased lipogenic substrate supply from other tissues, hepatic zonation of Irs1, and other factors, including ER stress, play crucial roles in increased hepatic de novo lipogenesis in MAFLD with hepatic insulin resistance." (PMID 33923817, 2021). "ER stress results in serine phosphorylation of IRS-1 via c Jun N terminal kinases (JNK), leading to insulin resistance." (PMID 33995826, 2021). "NF-κB and JNK, they, in turn, inhibited IRS-1 and AKT, indicating that TNFα induced insulin resistance." (PMID 34650665, 2021). "In the present study, exendin-4 accelerated IRS-1/AKT signaling and reduced insulin resistance in the HFD mouse hippocampus and primary cultured cortical and hippocampal neurons." (PMID 33859286, 2021). "The result of this sequence of molecular events is the inhibition of the insulin transducer signal via the phosphorylation of insulin receptor substrate 1 (IRS1) in serine, leading to insulin resistance in the liver, adipose, and muscle tissues." (PMID 34828808, 2021). "Administration of a genistein-rich diet to high-fat-high-fructose fed mice improved the hepatic insulin resistance by abolishing the increased p-(Ser)-IRS-1 and -2 levels and p-S6K1, as well as through the stimulation of IR, IRS-1 and -2, PI3K, AKT and AMPK." (PMID 34208379, 2021). "Recent studies have demonstrated that abnormal serine phosphorylation of IRS-1 is commonly observed in the brain of AD patients, and the reduced expression of IRS-1 results in insulin resistance in the brain." (PMID 33435277, 2021). "One potential mechanism is that elevated BCAAs levels lead to activation of the mTOR/S6K1 pathway and serine phosphorylation of IRS1, contributing to inhibition of insulin-induced PI3K activation and insulin resistance." (PMID 34419103, 2021). "The subsequent changes in insulin signaling, especially IRS-1, indicate that the link between the adipose tissue and skeletal muscle plays a critical role in the improvement of HFD-induced muscular insulin resistance by d-allulose in Wistar rats." (PMID 34684891, 2021). "Pin1 also positively regulates insulin-induced phosphorylation of IRS-1: Pin1 deletion inactivates IRS-1, thus leading to insulin resistance." (PMID 33537091, 2021). "Brain insulin resistance-related exosomal protein biomarkers were total insulin receptor substrate-1 (t-IRS-1), P-serine 312-IRS-1 (p-S312-IRS-1), P-tyrosine-IRS-1 (p-Y-IRS-1), and p-S312-IRS-1/p-Y-IRS-1." (PMID 34356604, 2021). "These events prevent serine kinase phosphorylation of IRS-1/IRS-2 and thus protect the cells from insulin resistance." (PMID 33917607, 2021). "The elevation of PI3K, p-IRS-1, p-Akt, p-AS160 and GLUT4 indicated the alleviation of insulin resistance through the PI3K/Akt signaling pathway." (PMID 33435282, 2021). "These inflammatory activation impairs insulin receptor substrate-1 (IRS-1) function and downstream insulin/PI3K pathway to prevent glucose uptake, inducing to insulin resistance in adipocytes." (PMID 34571976, 2021). "And future research will be required to clarify the relationship between ser(P)-IRS-1 and tyr(P)-IRS-1 and their impact on the regulation of brain insulin resistance." (PMID 34149862, 2021). "Accordingly, EGCG administration to triglyceride-infused rats ameliorated insulin resistance in WAT and soleus skeletal muscle by increasing p-AKT, p-AMPK and GLUT-4 levels, and decreasing p-(Ser307)-IRS-1, PKCθ translocation and oxidative stress." (PMID 34208379, 2021). "The serine phosphorylation of IRS-1 (Ser-307 and Ser-636 sites), which counteracted IRS-1 tyrosine phosphorylation and contributed to insulin resistance 53, was enhanced by HFD but suppressed by NR in WT mice but not in Fndc5-/- mice." (PMID 33754067, 2021). "JNK1-mediated disruption of insulin receptor/insulin receptor substrate 1 (IRS1) interaction and the resulting insulin resistance are dependent on IRS1 phosphorylation at both Ser302 and Ser307." (PMID 34959870, 2021).
Insulin resistance (continued). "Further, in vitro experiments using MIN6 cells showed that AOS regulated INS-R, IRS-1, IRS-2, and Glut4 protein and mRNA levels and attenuated insulin resistance and cell apoptosis." (PMID 34497509, 2021). "Insulin receptor substrate 1 (IRS1) was shown to be another GRK2 substrate, resulting in reduced glucose uptake and thereby insulin resistance." (PMID 33430208, 2021). "In contrast, cells exposed to chronic hyperinsulinemia will upregulate IR, IRS1, and PI3K activity, while inhibiting Akt phosphorylation, contributing to chronic insulin resistance and high blood sugar seen in obesity and diabetes." (PMID 39087082, 2021). "TNF-α has also been shown to be involved in the onset of insulin resistance by increasing FFA levels, inhibiting the insulin receptor and insulin receptor substrate-1 (IRS-1) production and inducing IRS-1 Ser/Thr phosphorylation." (PMID 33535496, 2021). "HFD‐induced obesity also decreased the expression of IRS‐1, indicating that HFD induced insulin resistance." (PMID 34676967, 2021). "IL-1α and IL-1β have been reported to impair insulin signaling by altering tyrosine phosphorylation of insulin receptor substrate (IRS-1 and IRS-2), which leads to insulin resistance." (PMID 33924165, 2021). "The development of insulin resistance is characterised by an increase in NF-κB, MAPK, and IRS-1 serine phosphorylation." (PMID 33557218, 2021). "In details, the animal studies revealed that the activation of JNK-1 by WNT5A impairs the activity of a target protein called insulin receptor substrate-1 (IRS-1) leading to suppressed insulin signaling and development of insulin resistance." (PMID 34184187, 2021). "In diabetic rats, HGSD ameliorated insulin resistance by increasing GLUT4 translocation and phosphorylation of IRS1 and AKT, while decreasing GC levels in skeletal muscle." (PMID 32792855, 2020). "-Inhibition of miR-122 via inhibition of JNK pathway and restoring the function of IRS1/IRS2 and insulin signaling. -Abrogated the insulin resistance observed in mice under high fat diet." (PMID 33585535, 2020). "By inhibiting insulin-stimulated tyrosine phosphorylation of insulin receptor and insulin receptor substrate-1, TNF-α can play a crucial role in systemic insulin resistance and also decipher a clear link between obesity, insulin resistance and T2D." (PMID 32188105, 2020). "Phosphorylation of serine 307 of IRS-1 inhibits tyrosine phosphorylation of IRS-1 and leads to insulin resistance." (PMID 32964053, 2020). "Another theory also indicates IRS1/2-PI3K-Akt signaling, which is activated by an interaction between adiponectin and APPL1 lowering insulin resistance." (PMID 32059381, 2020). "The main elements of IST such as Akt, IRS, IRS-1, and GSK-3 are under the influence of free radicals that are downregulated by the oxidative stress thereby impairing insulin sensitivity leading to insulin resistance and DM." (PMID 32215179, 2020). "With regard to kidney damage, BHID reduced fibrosis, inflammation, and insulin resistance through the inhibition of TGF-β1 and COX-2 expression, and the activation of Akt and IRS-1 compared with metformin." (PMID 32508632, 2020). "IL-6 downregulates glucose transporter 4 expression and insulin receptor substrate-1 (IRS-1), resulting in reduced transport of glucose into cells (including myocytes) and aggravation of insulin resistance." (PMID 33222694, 2020). "Studies have shown that ER stress can reduce the phosphorylation of IRS-1 and Akt, decrease the expression of oxygen-regulated protein 150 (ORP150), which prevents ER stress; and induce insulin resistance." (PMID 32082422, 2020). "Insulin resistance may contribute to chemotherapy resistance in individuals with colon cancer; as such, two colon cancer cell lines were used to determine whether the expression of IRS‐1 would affect the half maximal inhibitory concentration (IC50) of oxaliplatin after chronic insulin treatment." (PMID 32248666, 2020).
Insulin resistance (continued). "Phosphorylation of IRS-1 at serine sites and decreased phosphorylation of AKT result in disrupted insulin signaling and induction of insulin resistance." (PMID 31679138, 2020). "BCAAs were shown previously to be involved in several pathways of insulin resistance, including fatty acid oxidation, mTOR, JNK and IRS1 pathways." (PMID 32972433, 2020). "The fact that sodium vanadate, an inhibitor of phosphorylation of IRS-1ser307, can recover insulin secretion indicates that high levels of T3 can inhibit insulin signal transduction in β-cells via the IRS-1/PI3-K/Akt pathway and result in insulin resistance." (PMID 32774144, 2020). "The decreased IRS1 expression and increased IRS2, that are key substrate for PI3K, were found in insulin resistance state in adipocytes." (PMID 32932777, 2020). "In molecular studies, mTORC1 was shown to be upstream of insulin receptor substrate 1 (IRS-1) Ser phosphorylation residue, inducing insulin resistance." (PMID 32444657, 2020). "Western blot analysis demonstrated that umbelliferone administration markedly increases the phosphorylation of InsR, IRS-1, AKT, PI3K, and GSK-3β, suggesting an ameliorative effect of umbelliferone against insulin resistance." (PMID 33568996, 2020). "In other studies, acute induction of muscle insulin resistance increased DAG content, PKCθ activation, and increased phosphorylation of IRS1 serine 1,101, concurrent with inhibition of IRS1 and Akt2 phosphorylation." (PMID 33038072, 2020). "The production of TNF-α and IL-6 cytokines by macrophages leads to increased serine phosphorylation of insulin receptor substrate-1 (IRS-1), resulting in insulin resistance in the muscle and liver." (PMID 33105775, 2020). "Additionally, JNK1 phosphorylates IRS2 on Ser/Thr residues, which could also explain why mutation on one IRS1 residue did not prevent obesity-induced insulin resistance." (PMID 32183037, 2020). "As commonly reported, palmitic acid (PA), a kind of saturated fatty acid, is well-known to induce insulin resistance in C2C12 myotubes, which is characterized with an impaired Irs1-Akt signal pathway." (PMID 31833538, 2020). "Visfatin reduced the levels of insulin-signaling proteins, including p-IR, p-IRS-1 (Tyr612), p-AKT, and p-GSK-3α/β, triggering insulin resistance." (PMID 31396538, 2019). "The mechanism of insulin resistance in AD is also related to insulin-like growth factor 1 (IGF-1) resistance, and insulin receptor substrate 1 (IRS-1) disability, probably triggered by Aβ oligomers." (PMID 31428627, 2019). "Consistent with this, our data demonstrated that DYRK1A ameliorated insulin resistance in both SY5Y and primary neurons by elevating IRS-1 protein." (PMID 31723029, 2019). "For example, TNF-α over expression with obesity signals through IκB kinase β to phosphorylate IRS-1 and IRS-2 to promote insulin resistance, which in turn promotes liver TG accumulation." (PMID 30730895, 2019). "Data obtained from western blotting showed that LPS decreased the relative expression levels of IRS-1, PI3K, AKT and phosphorylation of AKT, contributing to insulin resistance." (PMID 31839747, 2019). "ER stress significantly contributes to the development of insulin resistance by impairing insulin signaling through the activation of JNK, followed by phosphorylation of Ser307 in IRS1." (PMID 31246177, 2019). "We identified that the induced insulin resistance in 3T3-L1 cells was ameliorated in the presence of cAT-MSC CM by measuring mRNA and protein expression levels of IRS-1 and GLUT4." (PMID 30445954, 2018). "Relative protein expression levels of IRS-1 and GLUT4 were augmented in the cAT-MSC CM treatment group compared to insulin resistance models, indicating beneficial effects of cAT-MSC to DM, probably by actions of secreting factors." (PMID 30445954, 2018). "Gene expression levels of insulin receptor substrate-1 (IRS-1) and glucose transporter type 4 (GLUT4) were used as indicators of insulin resistance." (PMID 30445954, 2018).
Insulin resistance (continued). "Both systemic IRS1 null mice and IRS2 null mice displayed insulin resistance, indicating both are irreplaceable." (PMID 30602666, 2018). "It has been shown that p70S6K downstream of TORC1 can phosphorylate and inhibit the insulin receptor substrate IRS1 and that sustained activation of TORC1 leads to depletion of IRS1 and IRS2 and insulin resistance." (PMID 28643116, 2018). "Inflammatory adipokine TNF-α is one of the factors responsible for this insulin resistance through activation of TNF receptor-JNK signaling pathway, resulting in the phosphorylation of serine residue of IRS-1." (PMID 29872751, 2018). "Dysfunction of IRS1 and IRS2 in different tissues contributes local, or even systemic insulin resistance, and pathogenesis of metabolic diseases." (PMID 30602666, 2018). "TNF-α, IL-6, and PKC, as well as IK kinase, cause serine phosphorylation of downstream IR substrate family members IRS-1, inhibiting phosphatidylinositol 3-kinase (PI3K) and serine/threonine kinase B (AKT), which leads to insulin resistance." (PMID 29599810, 2018). "We evaluated the improvement of insulin resistance and studied the effect of Modified Sanzi Yangqin Decoction on IRS-1, p-IRS-1(Tyr895), and PTP1B, key molecules involved in the insulin signal transduction pathway." (PMID 29721029, 2018). "Consistent with previous study, elevated p-IRS-1/IRS-1 protein expression, and decreased Akt Thr308 phosphorylation were observed in TRIM31−/− mice with impaired glucose tolerance and insulin resistance." (PMID 29497383, 2018). "As a result, both IRS-1 and GLUT4 mRNA levels showed similar tendencies through the differentiation to insulin resistance induction, but the degree of alterations was greater in GLUT4." (PMID 30445954, 2018). "It has been suggested that chronic hyperinsulinemia activates p38 (p38α MAPK mitogen-activated protein kinase) which can reduce IRS1 and IRS2 proteins by promoting their ubiquitination and/or degradation, resulting in insulin resistance." (PMID 30602666, 2018). "These intermediates induce insulin resistance due to multiple mechanisms, such as impairing pyruvate dehydrogenase (PDH), inhibiting insulin receptor substrate 1 (IRS-1) and glucose transporter type 4 (GLUT4) expression." (PMID 29909553, 2018). "TNF-α has been also involved in the occurrence of insulin resistance through the rise of FFA levels, inhibition of the insulin receptor and insulin receptor substrate-1 (IRS-1) production and induction of IRS-1 Ser/Thr phosphorylation." (PMID 30294279, 2018). "It was observed that the development of insulin resistance was characterized by increased levels of NF-κB, MAPK, and insulin receptor substrate 1 (IRS-1) serine phosphorylation." (PMID 29492183, 2018). "Both IRS-1 and GLUT-4 mRNA expression levels were significantly increased after cAT-MSC CM treatment in the insulin resistance model." (PMID 30445954, 2018). "This is a global transcriptional cofactor that enhances FOXO1-mediated gene expression, acetylates IRS1, 2, and subsequently impairs IRS interaction with insulin receptors, resulting in insulin resistance." (PMID 30602666, 2018). "Decreased GLUT4 expression and cell membrane localization, increased IRS-1 phosphorylation at Ser307 and decreased AKT phosphorylation at Ser473 after insulin stimulation have been well documented in insulin resistance." (PMID 29601606, 2018). "To investigate the effects of METRNL on palmitate-induced insulin resistance, we examined the effect of METRNL on insulin-stimulated IRS-1 and Akt phosphorylation and glucose uptake." (PMID 30213948, 2018). "TNF-α induces serine phosphorylation in insulin receptor substrate-1 (IRS-1), resulting in the inhibition of tyrosine kinase activity in the insulin receptor and leading to insulin resistance and hyperinsulinemia." (PMID 30134857, 2018).
Insulin resistance (continued). "To further explore the hepatoprotective mechanism of TF, we tested the expression of IRs-1, Akt, CYP2E1, and JNK in liver tissues, which are involved in insulin resistance and oxidative stress." (PMID 30275422, 2018). "These lipid derived products, which include ceramides and Di-Acyle glycerol (DAG), induce insulin resistance via de-phosphorylation of protein kinase B (PKB) and phosphorylation of a serine residue of insulin receptor substrate 1 (IRS-1)." (PMID 28898202, 2017). "More detailed analysis and understanding of the roles of miR-96 in diet-induced insulin resistance can be found in "Induction of miR-96 by dietary saturated fatty acids exacerbates hepatic insulin resistance through the suppression of INSR and IRS-1"." (PMID 29124099, 2017). "In peripheral insulin resistance, JNK is one of the most important stress-activated kinases, which is involved in IRS1 Serine phosphorylation." (PMID 28386117, 2017). "To investigate the mechanisms through which EPF inhibited insulin resistance in HFD group, we evaluated the IRS-1(Ser 307) phosphorylation level in mouse livers." (PMID 28867797, 2017). "The upregulation of miR-96 in SFA palmitate-treated hepatocytes was recently reported to downregulate IRS-1 expression by binding to its 3′UTR regions on mRNA, leading to hepatic insulin resistance." (PMID 29124099, 2017). "As a downstream signaling mechanism of IRS-1, the alteration of Kinase B/AKT (AKT) activity is one key characteristic of insulin resistance." (PMID 28790390, 2017). "In this context, Charbonneau and Marette showed that the covalent link of peroxynitrite (ONOO-) to IR, IRS-1, IRS-2 and Akt is also involved with insulin resistance after lipid infusion." (PMID 28835706, 2017). "Taken together, IRS-1 phosphorylation at the Y612 site is critical in both Akt activation and AMPK activation, emphasizing the roles of C1-Ten and its inhibitor, DHTS, in insulin resistance." (PMID 29259227, 2017). "In accordance with INSR and IRS-1, AKT phosphorylation was significantly reduced (P<0.05) in WT FF-fed mice, co-substantiating insulin resistance." (PMID 28406477, 2017). "To evaluate the effects of PDX on palmitate-induced insulin resistance, we investigated the effect of PDX on levels of insulin-stimulated Akt and IRS-1 phosphorylation and glucose uptake." (PMID 28469249, 2017). "At the same time, IKK is the serine kinase of insulin receptor and IRS-1, which can active the phosphorylation of IRS1-Ser307, and result in insulin resistance." (PMID 29240812, 2017). "Elevated BCAAs might lead to hepatic insulin resistance either directly by activating gluconeogenesis or indirectly through persistent activation of mTOR complex 1 (mTORC1), which promotes the inhibitory serine phosphorylation of insulin receptor substrate 1 (IRS-1)." (PMID 28640216, 2017). "Klotho inhibits signals of insulin/IGF-1 receptors (IR/IGF-Rs), and insulin receptor substrate 1 (IRS1), and induces insulin resistance." (PMID 27861640, 2016). "NAC neutralized the effect of HUA-induced phospho-IRS1 (Ser307) activity, which demonstrates a critical role of oxidative stress in the effect of HUA on insulin resistance." (PMID 26836389, 2016). "In insulin resistance, the signaling cascade via IRS2 seems to be impaired while the signaling cascade via IRS1 seems relatively intact." (PMID 27247938, 2016). "Using animal models of insulin resistance and T2DM, Mima and colleagues showed an attenuation of glomerular IRS1 expression, IRS1 phosphorylation, and glomerular endothelial signaling." (PMID 27247938, 2016). "In palmitate-induced insulin resistance of L6 myotubes, APL treatment markedly up- regulated phosphorylated insulin receptor substrate-1 and protein kinase B, along with a corresponding increase of glucose uptake capacity." (PMID 27391974, 2016).